RNU6-890P (RNA, U6 small nuclear 890, pseudogene)
Gene: Small nuclear RNA gene on chromosome 6 (42,664,162 to 42,664,268, forward strand). Ensembl gene ENSG00000206848.
Homologues: Orthologues: chimpanzee U6 (99% identical), macaque U6 (94% identical). Paralogues in human: RNU6-39P (92% identical), RNU6-480P (92% identical), RNU6-774P (92% identical), RNU6-21P (91% identical), RNU6-33P (91% identical), RNU6-38P (91% identical), RNU6-86P (91% identical), RNU6-1 (90% identical), RNU6-2 (90% identical), RNU6-3P (90% identical), RNU6-4P (90% identical), RNU6-5P (90% identical), and 1286 more.